CTAGE6 (CTAGE family member 6)
Synonyms: CTAGE6P; MGC41943
Tractability: Antibody: UniProt predicts a signal peptide or a membrane-spanning region.
Gene: Protein-coding gene on chromosome 7 (143,755,089 to 143,757,696, reverse strand). Ensembl gene ENSG00000271321.
Subcellular location: Membrane
Gene Ontology:
Biological process: endoplasmic reticulum to Golgi vesicle-mediated transport; protein secretion; vesicle cargo loading
Cellular component: endoplasmic reticulum exit site; endoplasmic reticulum membrane; membrane
Genetic constraint (gnomAD): Loss-of-function variants: 2 observed, 18.23 expected, observed/expected ratio (o/e) 0.11, 90% interval 0.044 to 0.34. The synonymous counts are far from expectation, so gnomAD's model fits this gene poorly and the ratio says little. Missense variants: 44 observed, 218.87 expected, observed/expected ratio (o/e) 0.2, 90% interval 0.16 to 0.26. Synonymous variants: 6 observed, 65.86 expected, observed/expected ratio (o/e) 0.0911, 90% interval 0.049 to 0.18.
Homologues: Orthologues: dog MIA2 (76% identical), mouse Mia2 (68% identical), rat Mia2 (67% identical), Drosophila melanogaster Tango1 (21% identical). Paralogues in human: CTAGE15 (99% identical), CTAGE8 (97% identical), CTAGE4 (96% identical), CTAGE9 (95% identical), MIA2 (82% identical), CTAGE1 (75% identical), MIA3 (26% identical), SPZ1 (8% identical), MIA (2% identical), OTOR (1% identical).